CTSB (cathepsin B)
Diseases named in the same sentence as CTSB in open-access papers (continued):
Sharing a sentence is not in itself a finding about the gene and the disease.
periodontitis (22 papers, 2013 to 2026). An acute or chronic inflammatory process that affects the tissues that surround and support the teeth. "In fact, both AD patients and chronic periodontitis-associated AD patients display elevated serum CTSB that correlates with the extent of cognitive deficits." (PMID 36970896, 2023). "In chronic periodontitis-associated AD patients, CTSB in serum was higher than controls by 43%." (PMID 36970896, 2023). "Recent investigations have suggested that cathepsin B may be implicated in the development of periodontitis." (PMID 37334378, 2023). "Therefore, VEGF and cathepsin B secreted by HGFs should induce the angiogenic cascades in periodontitis lesions cooperatively by affecting angiogenesis-associated cells such as endothelial cells." (PMID 31968635, 2020). "Usually, it takes 10 years from diagnosis of periodontitis to become a risk factor for AD, so there could be a steady increase in Cathepsin B overtime after the initial diagnosis of periodontal disease." (PMID 32973486, 2020). "Cathepsin B could be a potential biomarker to make stronger associations with periodontitis and AD." (PMID 32973486, 2020). "Although NLRP3 and inflammatory cytokine levels increased in periodontitis, they were effectively reduced after CTSB inhibition in the periodontal region." (PMID 41869360, 2026). "Key periodontitis-related mediators involved in AD pathogenesis are cathepsin B, gingipain, LPS, TNF, and IL-6." (PMID 40559320, 2025). "Moreover, pertinent studies have confirmed that cathepsin B consolidated the causative link between LPS and AD, and it’s anticipated that it will serve as a possible therapeutic target for avoiding AD initiation and pathological progression associated with periodontitis." (PMID 37334378, 2023). "verified that the equilibrium between cathepsin B and its inhibitor cystatin C is upset when P. gingivalis, the primary pathogen of periodontitis, infects the epithelium." (PMID 37334378, 2023). "These mouse studies are relevant to clinical periodontitis, since periodontitis patients display elevated serum CTSB that correlates with cognitive deficits." (PMID 36970896, 2023). "CTSB participates in Aβ production in neurodegenerative disease models of periodontitis, AGE, and MPS I expressing Wt AβPP." (PMID 36970896, 2023). "CTSB KO in the neuroinflammatory periodontitis model of AD showed that CTSB participates in neuronal Aβ production and drives memory deficits." (PMID 36970896, 2023). "Cathepsin B is also engaged in the degradation of collagen in the periodontal tissue of patients with periodontitis." (PMID 37334378, 2023). "Significant results showed that CTSB participates in PgLPS-induced periodontitis and memory deficits." (PMID 36970896, 2023). "KO of the CTSB gene in the periodontitis model of AD (PgLPS mice) resulted in significant improvements in memory deficits in middle-aged mice of 12 months old, but not in young 2-month-old mice, treated with PgLPS for 5 weeks." (PMID 36970896, 2023). "Increased levels of neutrophile proteases (elastase, protease 3 and cathepsin B) can contribute to significant depletion of SLPI in the infected periodontitis sites in those patients." (PMID 36481656, 2022). "Previously, it has been shown that levels of cathepsin B and L increase in the gingival crevicular fluids (GCFs) of patients with periodontitis." (PMID 31968635, 2020). "For Cathepsin B, our future study was to check if their quantity varies during aging and/or as periodontitis diagnosis timeline increases." (PMID 32973486, 2020). "Based on these findings, we hypothesized that regulating the secretion of cathepsin B and L from HGFs in periodontal inflammatory lesions could be crucial for managing the pathogenesis of periodontitis." (PMID 40135201, 2025). "Additionally, the results of immunohistochemical staining suggested that the levels of cathepsin B protein significantly increased in the periodontitis group, which were partially reversed following TTM treatment." (PMID 38892077, 2024).
periodontitis (continued). "The particular inhibitor of cathepsin B may be a successful way to slow the course of periodontitis and repair periodontal tissue, given the involvement of cathepsin B in collagen expression." (PMID 37334378, 2023). "Notably, cognitive deficits of periodontitis patients correlate with increased levels of cathepsin B." (PMID 36970896, 2023). "Models of chronic periodontitis-associated AD, advanced glycation end (AGE) products, and Mucopolysaccharidosis type I (MPSI) described in this section provide evidence for participation of CTSB in Aβ production in AD-related neurodegenerative conditions." (PMID 36970896, 2023). "Notably, the higher levels of serum CTSB corelated with reduced Mini-Mental State Examination scores of cognitive function in these periodontitis AD patients." (PMID 36970896, 2023). "Cathepsin B can be detected in the GCF of patients with periodontitis." (PMID 37334378, 2023). "Therefore, cathepsin B knockout in a mouse model of periodontitis was assessed for predicted improvements in memory deficits." (PMID 36970896, 2023). "CTSB deficiency by gene knockout (KO) resulted in improved memory deficits in a transgenic AD model expressing hAβPP-695 and in a non-transgenic chronic-periodontitis-associated AD model." (PMID 36970896, 2023). "Additionally, IL-6 significantly increases the production of VEGF, bFGF, and cathepsin B in human gingival fibroblasts and synergistically induces angiogenesis in periodontitis lesions." (PMID 36275775, 2022). "Furthermore, due to the function of cathepsin B in the degradation of collagen in periodontal tissue, we could postpone the advancement of periodontitis and repair periodontal tissue using a particular inhibitor of cathepsin B." (PMID 37334378, 2023). "The levels of cathepsin B were observed to increase in periodontitis when compared to gingivitis, despite similar GCF flow, and thus differentiate chronic gingivitis from periodontitis." (PMID 24490073, 2013). "Li X’s study proved that cathepsin B could reduce the expression of III and IV collagen in conditions of chronic inflammation such as periodontitis and oxidative stress through long-term activation of the TLR2/NF-κB signal." (PMID 37334378, 2023).
diabetes (21 papers, 2008 to 2025). "In addition, when metformin is used to treat diabetes, it can alleviate the onset and development of diabetes-associated hypertension by targeting the CTSB-ENaC pathway in collecting duct cells." (PMID 40129990, 2025). "Our data also suggests that co-existence of TCF7L2 variants and the SPINK1 and CTSB mutations, that predict susceptibility to exocrine damage, may interact to determine the onset of diabetes in TCP patients." (PMID 18706099, 2008). "In this study, PGs comprised one of the largest classes of phospholipids that showed differences in the amount enriched in uEVs from CtsB knockout mice after STZ-induced diabetes and hypertension." (PMID 38791000, 2024). "The aim of this study was to assess the impact of multilevel blocking of the RAAS, cathepsin B activity, and fibronectin accumulation in the glomerular in the rats diabetes model." (PMID 26089895, 2015). "In accordance with the results of NKAα1 overexpression, administration of Hamaudol prevented diabetes‐induced protein upregulations of ACSL4 and Cathepsin B, and induced autophagy in diabetic mouse aortae." (PMID 39902679, 2025). "Our study, performed on an animal model of diabetes mellitus induced by streptozotocin, aimed at assessing the impact of RAAS blocking on the activity of cathepsin B and the accumulation of FN." (PMID 26089895, 2015). "In addition, the pre-diabetes elderly were found to have increased NGF, BDNF, and cathepsin B, and decreased Beta-Amyloid 1–42 and homocysteine." (PMID 35455914, 2022). "Notably, three proteins (CPQ, CTSB, and GNS) were common among all four urinary signatures, and they were consistently excreted at higher rates in diabetes." (PMID 32453760, 2020). "We also evidenced an upregulation (7- to 9.7-fold) of genes encoding stefin A (StfA), the human ortholog of Cystatin A (CSTA), inhibitor of cathepsin B, H and L. StfA/CSTA was present in megakaryocytes and platelets and its expression increased during obesity and diabetes in rats and humans." (PMID 31270351, 2019). "In obesity (OB) and type 2 diabetes mellitus (T2DM), dysregulated myokine profiles characterized by reduced levels of irisin, brain-derived neurotrophic factor (BDNF), and cathepsin B (CTSB) have been reported and may contribute to the development of both sarcopenia and cognitive impairment." (PMID 41305665, 2025). "Treatment with CatL-inh protected diabetes-prone NOD mice from subsequently occurring diabetes such as high blood sugar and urine sugar while there was no therapeutic effect of cathepsin B inhibitor (CatB-inh) and cathepsin S inhibitor (CatS-inh)." (PMID 20877570, 2010).
Obesity (21 papers, 2007 to 2025). Accumulation of substantial excess body fat. "However, given the negative impacts of CTSB in the context of obesity and neuroprotective role of CTSB induced by exercise, future studies investigating the impact of exercise-induced release of CTSB in a model of obesity-associated AD will be of great importance." (PMID 41277875, 2025). "Another important myokine, CTSB, plays a crucial role in metabolic regulation in obesity and T2D, however CTSB-mediated effects appear to be in contrast with irisin action and actually exacerbate inflammation." (PMID 41277875, 2025). "During hypertrophy of WAT in obesity, CTSB is released into the cytosol, leading to autophagosome accumulation in WAT." (PMID 41277875, 2025). "Taken together, CTSL downregulation leads to complementary CTSB activation that can contribute to obesity-induced inflammation reactions in WAT." (PMID 31357643, 2019). "This study proposes an important mechanism of PLIN1 regulation and the possibility that CTSB might be a novel therapeutic target for obesity." (PMID 31959889, 2020). "In the case of cathepsin B, it was reported the secretion of this cysteine peptidase protein during adipocyte hypertrophy in the development of obesity promoting an excessive increase of autophagy, inflammation and macrophage infiltration contributing to metabolic syndrome." (PMID 32214011, 2020). "The function of cathepsin A in obesity is relatively unknown, however increases in expression of cathepsin B, D, K, S, and Z have previously been observed in obesity." (PMID 22947075, 2012). "Interestingly, the CTSB, ZNF646, and KAT8 genes have been associated with obesity." (PMID 40722297, 2025). "Thus, targeting cathepsin B/Nlrp3 inflammasome signaling axis could be a potential therapeutical strategy for treating cardiovascular diseases in obesity." (PMID 27689324, 2016). "Therefore, we hypothesized that PLIN1 protein in obese WAT is degraded by increased CTSB in adipocytes at the early stage of obesity, and that increased PLIN1 protein degradation and reduced PLIN1 gene expression contribute to the net protein loss in the late stage of obesity." (PMID 31959889, 2020). "Other potential obesity biomarkers were found among those proteins elevated in vesicles from lipid hypertrophied cells such as inter-alpha-trypsin inhibitor heavy chain H3 (ITIH3), Glut4, cathepsin B, osteopontin, CD36, or tissue factor." (PMID 32214011, 2020). "Therefore, we focused on cathepsin abnormalities, especially CTSL, CTSB and CTSD, as a mechanism of obesity-related lysosomal dysfunction in WAT and liver." (PMID 31357643, 2019). "Thus, alterations of CTSL and CTSB expressions in WAT are very complicated, likely depending on the degree of obesity status, type of food, timing of tissue sampling, or animal species." (PMID 31357643, 2019). "However, with obesity, we observed increased accessibility of genes involved in cell cycle regulation (ATM, CDKN1C, BCL2L11), autophagy (HSPA8, IRF8, PEX5), and protein catabolism (CDC34, CTSB, UBB)." (PMID 39872537, 2024). "Thus, we suggest that CMA and the release of CTSB accompanying LMP might play a role in PLIN1 degradation at the early and advanced stages of obesity, respectively." (PMID 31959889, 2020). "Therefore, the upregulation of basal FFA released via CTSB-induced PLIN1 degradation in adipocytes might contribute to a chronic state of low-grade inflammation, which is usually observed in obese WAT, leading to a pathological state of obesity." (PMID 31959889, 2020). "Therefore, given our result that PLIN2 protein is unchanged in CTSB-OE cells, it is likely that the obesity-induced upregulation of PLIN2 in WAT may be attributed to the increased infiltration of macrophages, rather than CTSB overexpression in obese adipocytes." (PMID 31959889, 2020).
acute pancreatitis (19 papers, 2013 to 2026). An acute inflammatory process that leads to necrosis of the pancreatic parenchyma. "CTSB is believed to colocalize with trypsinogen in the lysosomes, and subsequently activate the trypsinogen causing acute pancreatitis." (PMID 35872750, 2022). "Our research illustrated that increased calcium/cathepsin B activation/trypsinogen activation might be one of the mechanisms underlying acute pancreatitis induced by the proteasome inhibitor Bortezomib or Ixazomib in patients with multiple myeloma." (PMID 31221819, 2019). "Early studies have proposed a critical role of CTSB in intrapancreatic trypsinogen activation and the onset of acute pancreatitis." (PMID 41277866, 2026). "Our next aim was to elucidate the molecular mechanisms underlying our observation that under conditions of acute pancreatitis, CST3 lost its capacity to inhibit CTSB and CTSL-supporting disease progression." (PMID 39962054, 2025). "CTSB stored in the secretory compartment appears to be sufficient for this primary activation step in acute pancreatitis." (PMID 38709385, 2024). "Cysteine cathepsins such as cathepsin B and L play an important role in numerous diseases like acute pancreatitis or SARS-CoV-2 and therefore have high potential for the development of new therapeutics." (PMID 39680170, 2024). "Our results are consistent with observations from a previous study that showed an abundant CTSB activity in secretory vesicles even under physiological conditions, even prior to the onset of acute pancreatitis." (PMID 38709385, 2024). "While under physiological conditions this activation occurs inside the duodenum and is mediated by the brush border enzyme enterokinase, intracellular trypsinogen activation is initiated by the lysosomal hydrolase cathepsin B in acute pancreatitis." (PMID 38709385, 2024). "The co-localization of the lysosomal protease cathepsin B (CTSB) and the digestive zymogen trypsinogen is a prerequisite for the initiation of acute pancreatitis." (PMID 38709385, 2024). "The lysosomal cysteine protease cathepsin B (CTSB) plays a role in the intrapancreatic activation of trypsinogen in the onset of acute pancreatitis." (PMID 39680170, 2024). "For instance, the release of CTSB into the cytosol was shown to promote cell death in acute pancreatitis." (PMID 37996483, 2024). "Lysosomal cathepsin B interferes with phagocytosed zymogen, resulting in the activation of zymogen and the aggravation of acute pancreatitis." (PMID 36008957, 2022). "Research by Reinheckel T was more focused on the CTSB-related diseases, especially pancreatic diseases such as acute pancreatitis and pancreatic ductal adenocarcinoma." (PMID 35872750, 2022). "To date, there is inadequate evidence to suggest that the role of CTSB precedes that of enteropeptidase or that there is an interaction between the two in the occurrence and development of acute pancreatitis." (PMID 35872750, 2022). "Both ferret trypsinogen isoforms were readily activated by cathepsin B, the lysosomal cysteine protease responsible for intra-pancreatic trypsin activation in secretagogue-induced models of experimental acute pancreatitis." (PMID 30305676, 2018). "In contrast, we showed in the present study that caerulein-induced acute pancreatitis markedly increased the expression levels of all the three isoforms of the cathepsin B, namely the proenzyme and single- and double-chain forms." (PMID 28588238, 2017). "In contrast, however, the levels of the double- chain form of cathepsin B were lower in wild pancreas with caerulein-induced acute pancreatitis than in untreated wild pancreas." (PMID 28588238, 2017). "In caerulein-induced acute pancreatitis, the expression of all types of cathepsin B, including proenzyme, and the single- and double-chain forms (mature active form), was further increased in Rab7Δpan pancreas compared with untreated Rab7Δpan pancreas." (PMID 28588238, 2017).
acute pancreatitis (continued). "In other studies, N-acetylcysteine (a strong antioxidant) and the cathepsin B inhibitor CA-074me administered preoperatively demonstrated beneficial effects in experimentally induced acute pancreatitis." (PMID 23613780, 2013). "Whether CTSB leaked into the cytosol eventually contributes to the less favorable course of acute pancreatitis in Rab7 mice in the later disease course needs to be clarified further." (PMID 38709385, 2024). "Finally, the role of CTSB-mediated trypsinogen activation as the disease-relevant mechanism for acute pancreatitis needs to be re-assessed." (PMID 38709385, 2024). "CTSB may aggravate acute pancreatitis (AP) by activating the NLRP3 inflammasome and promoting caspase-1-induced pyroptosis." (PMID 36552871, 2022). "Cathepsin B is well known to stimulate trypsinogen in acute pancreatitis." (PMID 36068514, 2022). "Furthermore, we show that in the development of acute pancreatitis, trypsin and cathepsin B induced the release of contents in the granule co-localized lysosome into the cytosol." (PMID 31221819, 2019). "We therefore speculate that the lysosomal aberration observed in Rab7Δpan pancreas induces the increased active cathepsin B expression and marked elevation of intrapancreatic trypsin activity during acute pancreatitis." (PMID 28588238, 2017). "Its protective effect could be limited in taurocholate acute pancreatitis preceded by acute ethanol intake as evidenced by the differences in the cathepsin B, phospholipase A2 and lipase activities and by histopathological and ultrastructural findings." (PMID 23625750, 2013). "In pancreas-specific CTSB and CTSL double knockout undergoing with caerulein-induced acute pancreatitis intrapancreatic trypsin activity was increased while disease severity was not affected when compared to wildtypes or mice with pancreas-specific single CTSB or CTSL knockout." (PMID 38709385, 2024). "However, in acute pancreatitis, trypsinogen activation can be induced by cathepsin B." (PMID 36068514, 2022). "Thus, cytosolic calcium or cathepsin B could be considered to be the important point to ameliorate acute pancreatitis in patients treated with proteasome inhibitor." (PMID 31221819, 2019). "Both, cathepsin B (CTSB) and L (CTSL) are central regulators of protease activation in acute pancreatitis." (PMID 38709385, 2024). "Although cathepsin B is closely related to premature trypsinogen activation, the roles of ASAH1 in trypsinogen activation or acute pancreatitis are not fully understood." (PMID 36068514, 2022). "Therefore, ASAH1 may regulate the location of cathepsin B in acute pancreatitis." (PMID 36068514, 2022).